UBE2C (ubiquitin conjugating enzyme E2 C)
Diseases named in the same sentence as UBE2C in open-access papers (continued):
Sharing a sentence is not in itself a finding about the gene and the disease.
lung cancer (continued). "Since UBE2C-autophagy repression axis is evolutionarily deregulated in NSCLC and serves as a potential druggable target in lung cancer treatment, we phenotypically analyzed the consequences resulting from dysregulation of UBE2C-autophagy repression axis in lung cancer cells." (PMID 29904125, 2018). "miR-381, as the post-transcriptional repressor of UBE2C, is downregulated and co-exists with UBE2C activation in NSCLC, which is further validated followed by our results that showed that overexpressing miR-381 with its mimics significantly reduced the UBE2C expression in lung cancer cells." (PMID 29904125, 2018). "To address this, we first used an in vitro cell culture system and confirmed that UBE2C, but not UBE2S, is essential for the growth and survival of lung cancer cells harboring a mutant Kras." (PMID 36548081, 2023). "Knockdown of UBE2C, but not UBE2S, inhibits growth of lung cancer cells." (PMID 36548081, 2023).
prostate carcinoma (33 papers, 2012 to 2025). A carcinoma that arises from epithelial cells of the prostate gland. "More importantly, the UBE2C high expression caused a poor clinical outcome of patients in prostate cancer, gastric cancers, and lung adenocarcinoma." (PMID 35332135, 2022). "High expression of UBE2C caused a poor prognosis of patients in oral squamous cell carcinoma, prostate cancer, and glioma." (PMID 35332135, 2022). "The results showed that 7 genes were all associated with prostate cancer prognosis, but only UBE2C, TOP2A and CCNB1 were high expression in prostate cancer samples than normal prostate gland samples, the expression of PBK, CDKN3, AURKA, MKI67 were not." (PMID 33630978, 2021). "According to the results, UBE2C functioned as a risk factor in prostate cancer progression (HR 2.796; 95%CI 1.762–4.436; P<0.0001)." (PMID 33630978, 2021). "In other words, miR-381-3p impeded the expression and function of UBE2C to curb the progression of prostate cancer." (PMID 38818039, 2024). "UBE2C was pivotal for the progression of prostate cancer and the level of UBE2C was important to predict the prognosis of patients." (PMID 33630978, 2021). "Apparently, the level of UBE2C showed strong relationship with the differentiation and progression of prostate cancer and conspicuously correlated with the prognosis." (PMID 33630978, 2021). "Previous study has showed UBE2C was highly correlated with chemoresistance and radiotherapy resistance of prostate cancer." (PMID 33630978, 2021). "Through GSEA and univariate and multivariate analysis, the role of UBE2C in prostate cancer was explored completely." (PMID 33630978, 2021). "We have confirmed that the level of UBE2C was paralleled with the Gleason score of prostate cancer, early biochemical recurrence and poor clinical outcomes." (PMID 33630978, 2021). "It is essential for us to verify the importance of UBE2C in prostate cancer and explore the mechanism of UBE2C in regulating the development of prostate cancer by experimental approach." (PMID 33630978, 2021). "According to the validation results, UBE2C, which was highly expressed in prostate cancer, in particular castration-resistant prostate cancer." (PMID 33630978, 2021). "Gene Set Enrichment Analysis (GSEA) was performed to highlight the function of Ubiquitin-conjugating enzyme complex (UBE2C) in prostate cancer." (PMID 33630978, 2021). "GSEA showed UBE2C had played an important role in the pathway of prostate cancer, such as NOTCH signaling pathway, WNT-β-catenin signaling pathway." (PMID 33630978, 2021). "The mechanisms of UBE2C in promoting and regulating the development of prostate cancer deserve to be explored." (PMID 33630978, 2021). "According to our results, UBE2C highly expressed in prostate cancer, especially in castration-resistant prostate cancer and UBE2C was correlated with the neuroendocrine prostate cancer biomarkers, such as RB1 and LDHA." (PMID 33630978, 2021). "Based on the median expression of UBE2C, primary prostate cancer samples in GSE70770 were divided into low versus high group." (PMID 33630978, 2021). "It is of great worth to study the relationship between the expression of UBE2C and the treatment resistance of prostate cancer." (PMID 33630978, 2021). "On the contrary, miR-381-3p functions as a tumor suppressor gene in rectal cancer and prostate cancer through suppression of UBE2C." (PMID 32411707, 2020). "Of note, multiple genes hitherto known to be associated with prostate cancer progression were observed in the top list of upregulated entities including but not limited to MYBL2, ESM1, PBK, and UBE2C in PC3, and MMP1, CCL5, and STC1 in DU145." (PMID 31493351, 2019). "Herein, our results demonstrated that ICT treatment inhibit tumor development and progression of PCa in TRAMP mice by downregulating UBE2C expression in prostatic cancer tissues." (PMID 31646760, 2019). "UBE2C is considered a potent oncogene and is highly upregulated in castration-resistant prostate cancer." (PMID 29464047, 2018).
prostate carcinoma (continued). "We also examined transcription of an M phase cell cycle regulatory gene, UBE2C, previously shown to be important for growth of androgen-independent prostate cancer cells." (PMID 26509262, 2015). "Androgen receptor (AR) plays a pivotal role in prostate cancer development and progression, by mediating transcription of pro-mitotic genes, including UBE2C and cyclin D, resulting in prostate cancer cell proliferation." (PMID 26412853, 2015). "UBE2C has been shown to be a prominent oncogene in solid tumors, and it is found overexpressed in various types of solid tumors including late-stage prostate cancer." (PMID 25481872, 2015). "Collectively, these data suggest MED1 plays an essential role in the ARv567es induction of UBE2C and subsequent prostate cancer cell growth in an androgen-independent manner." (PMID 25481872, 2015). "A recent study showed that MED1 plays an essential role in chromatin looping at the castration-resistant prostate cancer-specific AR target UBE2C gene locus." (PMID 23887938, 2013). "One such example is the AR target gene UBE2C that promotes ligand-independent prostate cancer proliferation." (PMID 23704919, 2013). "It was reported that genomic amplification was a mechanism of increased UBE2C expression in colon cancer, thyroid carcinoma and prostate cancer." (PMID 23587173, 2013). "Therefore, UBE2C seems to be a key player in the regulation of mitotic slippage and a mediator in docetaxel resistance in prostate cancer." (PMID 37958776, 2023). "Cox regression analysis has indicated UBE2C could function as the independent prognostic factor of prostate cancer." (PMID 33630978, 2021). "Moreover, the expression level of UBE2C increased as T-stage and N-stage of prostate cancer improved." (PMID 33630978, 2021). "In brief, UBE2C, highly expressed in prostate cancer tissue, was identified as the real hub gene." (PMID 33630978, 2021). "In fact, only UBE2C was highly expressed in prostate cancer when compared with benign prostate tissue in TCGA and the expression of UBE2C was also in parallel with the Gleason score of prostate cancer." (PMID 33630978, 2021). "It indicated that targeting UBE2C may provide new therapy idea for prostate cancer, especially for castration-resistant prostate cancer." (PMID 33630978, 2021). "And the results showed that UBE2C was essential for predicting the disease-free survival of prostate cancer and may play an important role in prostate cancer." (PMID 33630978, 2021). "UBE2C was elevated in various cancers, including bladder, brain, CNS, cervical, colorectal, esophageal, gastric, head and neck, liver, lung, ovarian, pancreatic, and prostate cancers, as well as in lymphoma, melanoma, and sarcoma." (PMID 34858987, 2021). "Other research has confirmed the level of UBE2C, which could be regulated by miR-381-3p, was positive correlated with the proliferation of prostate cancer cells." (PMID 33630978, 2021). "Conspicuously, in PC-3 cells, UBE2C could recruit FOXA1 to its enhancers, that was mostly likely correlated with the expression of UBE2C and promoted the progression of castration-resistant prostate cancer." (PMID 33630978, 2021). "And there have been several researches focused on the mechanism of UBE2C in prostate cancer." (PMID 33630978, 2021). "Through comprehensive bioinformatics analysis, we concluded that UBE2C could drive the progression of prostate cancer, but the analysis in this paper still had some certain limitations." (PMID 33630978, 2021). "Castrate mice without IL-17 receptor C (IL-17RC) prostate had lower rates of cellular proliferation as well as lower UBE2C protein level, indicating that UBE2C might play a role in TME of prostate cancer." (PMID 34950739, 2021). "Moreover, the chromosomal loops of UBE2C have been reported to be a new therapeutic target in castration-resistant prostate cancer." (PMID 30634466, 2019).
prostate carcinoma (continued). "Furthermore, several genes have never been reported to be associated with MM, but they are oncogenes (e.g., TPX2 is related to gastric cancer and pancreatic cancer; UBE2C is related to prostate cancer and colorectal cancer)." (PMID 31886876, 2019). "Interestingly, the ubiquitin-conjugating enzyme 2C (UBE2C) is aberrantly increased in many cancer types and is reported to be casually involved in prostate cancer development and progression." (PMID 28415632, 2017). "For example, a study on prostate cancer found that the UBE2C oncogene interacts with two distal binding sites of Androgen Receptor (AR, an important protein in prostate cancer) only in Castration-Resistant Prostate Cancer (CRPC) cells but not in Androgen-Dependent Prostate Cancer (ADPC) cells." (PMID 24835279, 2014). "Given that CCAR1 is required for optimal recruitment of MED1 to AR-binding sites, it will be interesting to test whether CCAR1 also contributes to UBE2C locus looping and castration-resistant prostate cancer progression." (PMID 23887938, 2013). "Based on current study, UBE2C, which could not only drive prostate neoplasms progression but also could predict the prognosis of prostate cancer, was identified as the hub gene of prostate cancer." (PMID 33630978, 2021). "Thus, for instance, FOXA1 (Forkhead box protein A1), another member of the forkhead box protein family, was found bound in the exon 3 region of UBE2C gene and, in association with MED1 (mediator complex subunit 1), was capable of altering UBE2C expression levels in prostate cancer cells." (PMID 29596365, 2018). "CENPA expression tracks tightly with a number of previously identified prostate cancer pathogenesis factors including CENPF, UBE2C, and EZH2 (and Data Set S1)." (PMID 32371391, 2020). "Microarray analysis of prostate (cancer) specimens showed that, similarly to AR expression, UBE2C and BUB1B are significantly upregulated in CRPC tissue compared with benign tissues and androgen-sensitive primary prostate cancer and metastatic tissues." (PMID 30664691, 2019). "For instance, a UBE2C transcription inhibitor, CCI-779, and a UBE2C-proteasome inhibitor, Bortezomib, blocked cell cycle progression in prostate cancer cells and colorectal carcinoma, respectively." (PMID 24699941, 2014). "For example, MYBPC1, UBE2C and NUSAP1 have been previously reported to be differentially expressed throughout prostate cancer progression." (PMID 23826159, 2013). "We analyzed 14 additional genes, including the AR-activated genes PSA, FKBP51, ORM1, STAG, Nkx3.1, FASN, AQP3, KLK2, and UGT2B; the AR-repressed genes DKK and FST; and the castration-resistant prostate cancer AR-regulated genes CDC20, CDK1, and UBE2C." (PMID 22761715, 2012). "Interestingly, the manipulation of miRNAs, namely miR661-3p and miR-381-3p, has shown the ability to target UBE2C in NSCLC and prostate cancer cells, respectively, leading to reduced proliferation, invasion, and metastasis." (PMID 37958776, 2023). "It has been reported that phospho-MED1 mediates UBE2C locus looping in castration-resistant prostate cancer cells, but not in the androgen-dependent prostate cancer cells." (PMID 25481872, 2015). "UBE2C, PDZ-binding kinase (PBK), cyclin B1 (CCNB1), Cyclin-dependent kinase inhibitor 3 (CDKN3), topoisomerase II alpha (TOP2A), Aurora kinase A (AURKA) and MKI67 were identified as the candidate hub genes, which were all correlated with prostate cancer patient’ disease-free survival in TCGA." (PMID 33630978, 2021). "First, the role of UBE2C in prostate cancer has not been proven in vivo or in vitro." (PMID 33630978, 2021).
ovarian carcinoma (31 papers, 2016 to 2025). A malignant neoplasm originating from the surface ovarian epithelium. "In this study, we performed an integrated bioinformatic analysis and found that UBE2C was hypomethylation and overexpression in ovarian cancer, which was associated with advanced cancer stages and poor prognoses." (PMID 35804892, 2022). "We identified that UBE2C was hypomethylation and overexpression in ovarian cancer, which was associated with more advanced cancer stages and poor prognoses." (PMID 35804892, 2022). "It was also reported that the aberrant expression of UBE2C is associated with some gynecologic cancers, such as endometrial and ovarian cancers." (PMID 34577856, 2021). "The high expression of UBE2C was associated with a poor prognosis in breast, colon, liver, lung, and ovarian cancer." (PMID 34858987, 2021). "Taken together, our study may help us to understand the underlying molecular mechanism of UBE2C in pan-cancer tumorigenesis; it may be a useful biomarker for diagnosis, treatment, and monitoring, not only of ovarian cancer but a variety of cancers." (PMID 35804892, 2022). "UBE2C encodes an E2 ubiquitin-conjugating enzyme, is required for the destruction of mitotic cyclins and for cell cycle progression, and is involved in cancer progression (cervical cancer and ovarian cancer)." (PMID 33952272, 2021). "Of note, our team previously found that UBE2C might be associated with poor prognosis in ovarian cancer patients." (PMID 31942195, 2020). "Overexpression of UBE2C was associated with poor OS for ovarian cancer patients, and thus UBE2C might be a promising prognostic molecular biomarker and therapeutic target for ovarian cancer." (PMID 30453999, 2018). "It has been demonstrated that UBE2C plays a vital role in regulating the drug resistance of several types of cancers, such as cisplatin resistance in ovarian cancer and masitinib resistance in esophageal cancer." (PMID 38634120, 2024). "Overexpression of UBE2C in ovarian cancer correlates with adverse clinical outcomes, including elevated tumor grades and diminished survival rates." (PMID 39033780, 2024). "The silencing of UBE2C in ovarian cancer cell lines markedly reduces cell proliferation and augments apoptosis, primarily by inducing G2/M phase arrest and reducing CDK1 expression." (PMID 39033780, 2024). "A study of ovarian cancer cells showed that high UBE2C expression correlated with expression of CDK1." (PMID 37377594, 2023). "Ubiquitination and deubiquitination are known to be modulated during cancer progression, and high UBE2C expression portends poor survival in various cancers including node-positive breast cancer and ovarian carcinomas." (PMID 37377594, 2023). "Silencing UBE2C can significantly reduce the resistance of DDP-resistant ovarian cancer cell lines to DDP and promote their apoptosis." (PMID 37840753, 2023). "It has been reported that the expression of UBE2C is increased in DDP-resistant ovarian cancer cell lines." (PMID 37840753, 2023). "In a relevant study, the depletion of UBE2C was found to reduce the malignancy of ovarian cancer and reverse resistance to cisplatin by downregulating CDK1." (PMID 37986001, 2023). "A previous study by our group found that UBE2C was highly expressed in ovarian cancer and that downregulation of UEB2C induced higher apoptosis by blocking the G2/M transition." (PMID 35804892, 2022). "This was consistent with our prior report showing cell cycle arrest in ovarian cancer cells by UBE2C downregulation." (PMID 35804892, 2022). "We noticed that ovarian cancer and the other 16 cancers had a significantly higher mRNA expression of UBE2C than normal tissues from Oncomine, except for leukemia." (PMID 35804892, 2022). "This figure showed that ovarian cancer had the highest mRNA levels of UBE2C of almost all the cancers." (PMID 35804892, 2022).